GDNF (glial cell derived neurotrophic factor)
Diseases named in the same sentence as GDNF in open-access papers (continued):
Sharing a sentence is not in itself a finding about the gene and the disease.
schizophrenia (continued). "The effectiveness of CCRT in alleviating negative symptoms was associated with improvements in list recall, and GDNF may play a role in the observed effects of CCRT in patients with schizophrenia." (PMID 39886050, 2024). "Here, our analysis of the acute and chronic effects of methamphetamine, a known risk enhancer for psychosis, gave further insight into how GDNF expression may relate to susceptibility to schizophrenia." (PMID 37759827, 2023). "We found that 58 of the 214 DE genes had previously been associated with schizophrenia in either genome-wide association studies (GWAS) or in transcriptomic analyses from patients, suggesting that GDNF overexpression recapitulates a subset of the molecular abnormalities underlying schizophrenia." (PMID 35618883, 2022). "We asked whether elevated endogenous GDNF expression in mice is sufficient to induce striatal hyperdopaminergia and other schizophrenia-associated changes in the brain." (PMID 35618883, 2022). "GDNF is secreted from glial cells, and morphological and functional defects of glial cells may be associated with the pathogenesis of schizophrenia." (PMID 34763683, 2021). "In addition, in a diagnostic group comparison, CSF GDNF level was decreased in patients with schizophrenia compared with healthy controls." (PMID 32439851, 2020). "The inconsistency of previous studies on the association of BDNF and GDNF with schizophrenia may be related to the confounding effects of the severity of symptoms, age, gender, sample population, different stages of illness and medication history." (PMID 31420036, 2019). "Intriguingly, recent studies of neuropsychiatric disorders have reported that increased protein levels of GDNF or its polymorphism were observed in addiction, bipolar disorder, obsessive compulsive disorder, autism, schizophrenia, and attention deficit hyperactivity disorder." (PMID 29617307, 2018). "To date, a cohort of association analyses has suggested that certain GDNF polymorphisms might be linked to schizophrenia, a pervasive neurodevelopmental disorder." (PMID 24324616, 2013). "Therefore, it seemed particularly justified to explore whether some common (minor allele frequency [MAF] > 0.05) non-coding SNPs in the GDNF gene potentially influencing mRNA stability are associated with schizophrenia." (PMID 38674063, 2024). "The role of GDNF as a potent neurotrophic factor for midbrain dopamine neurons that promotes striatal dopamine release and re-uptake is particularly important given that cognitive dysfunctions in schizophrenia have been linked to aberrant dopaminergic transmission in the striatum." (PMID 38645418, 2024). "Therefore, more detailed longitudinal studies are required to determine if GDNF may be associated with the pathogenesis of schizophrenia and the response to pharmacological treatment." (PMID 31420036, 2019). "Glial cell line-derived neurotrophic factor (GDNF) has emerged as a potential biomarker for schizophrenia (SCZ)." (PMID 39881227, 2025). "This comprehensive approach aims to enhance our understanding of GDNF's role in schizophrenia and its potential as a biomarker for diagnosis and treatment." (PMID 39881227, 2025). "In human cerebrospinal fluid obtained from 69 first-episode psychosis subjects with schizophrenia, the level of GDNF was twofold elevated compared to 44 healthy controls." (PMID 41562905, 2025). "A previous study showed that serum levels of BDNF and GDNF were markedly lower in the first-episode drug-naïve patients with schizophrenia than in healthy controls." (PMID 39886050, 2024). "Given the importance of dopamine neurotransmission changes in schizophrenia during adolescence and adulthood, research has focused on GDNF’s role in its pathophysiology." (PMID 38645418, 2024). "Further research is needed to investigate the role of GDNF and its interaction with other neurotrophic factors in cognitive and clinical improvement in patients with schizophrenia." (PMID 39886050, 2024).
schizophrenia (continued). "Compared with the healthy controls, peripheral BDNF and GDNF serum levels were significantly reduced in patients with schizophrenia." (PMID 39886050, 2024). "Given its broad functional in the nervous system, GDNF has been considered to potentially contribute to the pathogenesis of mental diseases, including schizophrenia, known for dopaminergic system dysfunction." (PMID 38646100, 2024). "GDNF is important for dopaminergic neurons, and plays a critical role in the pathophysiology of schizophrenia." (PMID 39886050, 2024). "The first hints implicating potential correlations between GDNF and schizophrenia were based on the role GDNF is known to play in the development and survival of central dopaminergic neural circuitries at the cellular level." (PMID 38674063, 2024). "The changes in the gut microbiota result in the hypoactivity of N-methyl-d-aspartate (NMDA) and brain-derived neurotrophic factor (BDNF)/glial-cell derived neurotrophic factor (GDNF) receptors, which regulate brain plasticity, in schizophrenia patients." (PMID 37892465, 2023). "For example, serum of schizophrenia patients shows reduced levels of GDNF compared to healthy controls." (PMID 37251644, 2023). "A recently published study suggests that an increase in GDNF expression in the CNS, at around midgestation (E12.5), results in schizophrenia-like changes in dopamine metabolism and animal behaviour." (PMID 37759827, 2023). "This, combined with a well-known lack of high-affinity antibodies that exclusively recognize endogenous GDNF, has complicated the drawing of a firm conclusion on GDNF biology in schizophrenia." (PMID 37759827, 2023). "A recent study revealed that a 2–3-fold increase in endogenous GDNF expression in the adult striatum and the embryonic brain induces dopaminergic changes similar to that seen in schizophrenia." (PMID 37759827, 2023). "Taken together, the regulation of GDNF levels by antipsychotics and its impact on dopamine signalling and neuronal function in schizophrenia remain important directions for future research." (PMID 35618883, 2022). "To investigate the possible link between GDNF and schizophrenia in humans, we evaluated GDNF levels in the cerebrospinal fluid (CSF) from first episode psychosis (FEP) patients." (PMID 35618883, 2022). "Lastly, we found that GDNF levels are increased in the cerebrospinal fluid of first episode psychosis patients, and in post-mortem striatum of schizophrenia patients." (PMID 35618883, 2022). "In line with our findings, the results showed a highly significant increase in striatal GDNF mRNA levels in post-mortem striatum in individuals with schizophrenia compared to controls." (PMID 35618883, 2022). "Our data also suggests A2AR as a potential drug target in a subgroup of schizophrenia patients with elevated GDNF." (PMID 35618883, 2022). "It is important to note that the 2–3-fold increase in endogenous GDNF expression achieved in Gdnf cHyper mice is considerably higher than the ~20% average increase in GDNF levels in the CSF that we observed in schizophrenia patients." (PMID 35618883, 2022). "It seems that GDNF works through different systems in patients with schizophrenia and in healthy controls." (PMID 34763683, 2021). "For example, Tang and colleagues revealed a low BDNF and GDNF serum level in Chinese male patients with schizophrenia." (PMID 35095724, 2021). "In one study that explored GDNF serum levels in different psychiatric disease groups, serum GDNF levels were found to be lower in schizophrenia patients compared to control group participants." (PMID 34763683, 2021). "In the present study, serum GDNF levels were found to be lower in schizophrenia patients than in the healthy controls." (PMID 34763683, 2021). "CSF APP and GDNF levels were decreased in patients with schizophrenia, while CSF APP and NCAM-1 levels were decreased in patients with BD, compared with healthy controls." (PMID 32439851, 2020).
schizophrenia (continued). "Although there have been inconsistencies in the studies that investigated the BDNF and GDNF levels in patients with schizophrenia; the majority of the studies revealed that these two NFs are closely related to the pathological process of this disease." (PMID 31420036, 2019). "In our study, the chronic schizophrenia patients had received long-term antipsychotic treatment during hospitalization, which likely altered their serum GDNF levels to near normal levels." (PMID 31420036, 2019). "Our results add LI to the list of behaviors affected by chronic stress and support a role for GDNF deficits in stress-induced pathological behaviors relevant to schizophrenia and other psychiatric disorders." (PMID 29066960, 2017). "A genome-wide linkage study has first shed light on the GDNF as potential candidate gene in schizophrenia, followed by contradictory results from case-control association studies." (PMID 24324616, 2013). "Some studies have shown that the level of GDNF increased after 3 months of treatment in patients with first-episode schizophrenia, which was positively correlated with cognitive function, indicating that GDNF may have neuroprotective effects." (PMID 40251163, 2025). "The findings suggested that GDNF may be a promising biomarker and therapeutic target for schizophrenia." (PMID 39881227, 2025). "A significant limitation of the application of GDNF is that its overexpression is also detrimental, as it can lead to hyperdopaminergia, which may trigger the exacerbation of schizophrenia and the onset of psychosis." (PMID 41562905, 2025). "A decrease in GDNF levels was observed in patients with schizophrenia." (PMID 40251163, 2025). "Research on serum levels of GDNF in schizophrenia reveals several critical gaps." (PMID 39881227, 2025). "In murine models of schizophrenia, GDNF was shown to activate adenosine A2a receptor (A2AR), a G protein-coupled receptor that modulates dopaminergic signaling and could be a trigger for hyperdopaminergia." (PMID 41562905, 2025). "Serum GDNF levels showed an inverse correlation with brief psychiatric rating scale (BPRS) scores in unmedicated patients with schizophrenia, while patients with deficit schizophrenia performing better on cognitive tests exhibited higher-than-average serum GDNF levels." (PMID 38674063, 2024). "In support of this hypothesis, anti-NCAM1 autoantibodies disrupting the interaction of GDNF with NCAM1 could be detected in 5.4% of schizophrenia patients and injection of these antibodies precipitated schizophrenia-related symptoms in mice." (PMID 38674063, 2024). "Recent evidence suggests that abnormally high—about two-fold increase in endogenous GDNF expression—may drive schizophrenia in a subgroup of patients." (PMID 38920687, 2024). "Importantly, antipsychotic treatment improved schizophrenia symptoms and enhanced GDNF levels as well." (PMID 38674063, 2024). "Additionally, an increase in endogenous GDNF leads to schizophrenia-like behavioral abnormalities in mice, such as apathy or avolition." (PMID 38645418, 2024). "This study aimed to explore the efficacy of computerized cognitive remediation therapy (CCRT) on psychiatric symptoms, cognitive deficits, and serum levels of brain-derived neurotrophic factor (BDNF) and glial cell line-derived neurotrophic factor (GDNF) in patients with schizophrenia." (PMID 39886050, 2024). "It has also been demonstrated that a 2–3-fold increase in endogenous GDNF expression triggers schizophrenia-like conditions (including the expression of relevant genes and behavioral responses) and also imbalance the dopamine content between the prefrontal cortex and striatum." (PMID 38646100, 2024). "As outlined in the Introduction, plasma GDNF levels seem to be reduced in patients with schizophrenia, but only scarce and ambiguous information is available to date on genetic factors modulating the expression of GDNF at the transcriptional and post-transcriptional levels." (PMID 38674063, 2024).
schizophrenia (continued). "In the present study, increase in serum GDNF levels after CCRT suggests that GDNF may serve as a potential biomarker for the response to cognitive remediation in schizophrenia." (PMID 39886050, 2024). "Furthermore, serum GDNF levels in patients with deficit schizophrenia who performed better in cognitive tests were higher than the average." (PMID 39886050, 2024). "Serum levels of GDNF and BDNF were significantly lower in patients with schizophrenia compared to healthy controls at baseline (GDNF: 304.838 ± 18.236 pg/ml vs. 378.534 ± 24.397 pg/ml, p = 0.012; BDNF: 275.821 ± 21.447 pg/ml vs. 370.983 ± 33.849 pg/ml, p = 0.010)." (PMID 39886050, 2024). "Although the levels of GDNF are altered in both schizophrenia and ADHD children, both studies measured circulation levels of GDNF suggesting that this alteration might not be restricted to the cerebellum but a global nervous system impairment." (PMID 37251644, 2023). "Here, we analyzed changes in serum concentrations of cytokines (IL-1β, IL-2, IL-4, IL-6, IL-10, IL-21, APRIL, BAFF, PBEF/Visfatin, IFN-α, and TNF-α) and growth/neurotrophic factors (GM-CSF, NRG1-β1, NGF-β, and GDNF) in patients with schizophrenia in an exacerbation phase." (PMID 37239308, 2023). "Importantly, in mice, we established that a similar increase in GDNF results in schizophrenia-like molecular, neurophysiological, and behavioral changes, with increased presynaptic dopamine levels and release." (PMID 37759827, 2023). "Growth factors such as GM-CSF (granulocyte macrophage colony-stimulating factor), NRG1-β1 (neuregulin-1 beta 1), NGF-β (nerve growth factor beta), and GDNF (glial cell line-derived neurotrophic factor) are actively involved in inflammation processes and schizophrenia pathogenesis." (PMID 37239308, 2023). "Our previous analysis using a hyper-sensitive endogenous GDNF protein detection system, available at Olink Ltd., Uppsala, Sweden, showed that GDNF levels correlate with schizophrenia in the CSF and that GDNF mRNA levels are increased in the striatum in schizophrenia patients." (PMID 37759827, 2023). "However, the role of the GDNF system in striatal hyperdopaminergia observed in schizophrenia has remained obscure." (PMID 37759827, 2023). "Here, we hypothesized that increased expression of endogenous GDNF could induce dopaminergic abnormalities that resemble those seen in schizophrenia." (PMID 35618883, 2022). "This suggests that selective A2AR antagonism may alleviate some of the symptoms of schizophrenia, with a potential specific relevance for a subgroup of patients with high striatal GDNF levels." (PMID 35618883, 2022). "Together, these results show an overall average higher GDNF expression in schizophrenia patients and suggest that elevated GDNF may contribute to the disease, particularly in patients with highest elevation of GDNF levels." (PMID 35618883, 2022). "In addition, GDNF, which was reported that the endogenous dosage correlates with clinical severity in schizophrenia, was upregulated in oligodendrocytes." (PMID 36232882, 2022). "Our results reveal a possible contributor for increased striatal dopamine signalling in a subgroup of schizophrenia patients and suggest that GDNF—A2AR crosstalk may regulate dopamine function in a therapeutically targetable manner." (PMID 35618883, 2022). "Thus, two-fold adult onset increase in endogenous GDNF expression in the striatum is sufficient to trigger schizophrenia-like hypodopaminergia in the PFC, likely via increased activity of striatal dopamine signalling." (PMID 35618883, 2022). "Another study found that serum GDNF levels in schizophrenia patients with a movement disorder called tardive dyskinesia (TD), which is thought to be due to long-term antipsychotic drug use, were lower than in normal controls and patients with schizophrenia without TD." (PMID 34763683, 2021).
schizophrenia (continued). "CSF amyloid precursor protein (APP) and glial cell-derived neurotrophic factor (GDNF) levels were significantly lower in patients with schizophrenia, and CSF APP and neural cell adhesion molecule (NCAM)-1 levels were significantly lower in patients with BD, than in healthy controls (all p < 0.05)." (PMID 32439851, 2020). "However, one study has shown that higher GDNF levels result in more severe attention deficit in schizophrenia outpatients." (PMID 31420036, 2019). "Furthermore, the biological mechanisms linking GDNF to schizophrenia are poorly understood." (PMID 39881227, 2025). "Additionally, CCRT ameliorated the decrease in serum GDNF levels in patients with schizophrenia." (PMID 39886050, 2024). "Additionally, GDNF might be involved in the specific effects of CCRT on patients with schizophrenia." (PMID 39886050, 2024). "We find that increased levels of GDNF are sufficient to induce altered dopamine signalling, including striatal hyperdopaminergia and cortical hypodopaminergia, as well as behavioural deficits and gene expression alterations similar to individuals with schizophrenia." (PMID 35618883, 2022). "Therefore, we hypothesized that A2AR inhibition could alleviate some of the endogenous GDNF-induced schizophrenia-like features." (PMID 35618883, 2022). "Therefore, GDNF may be potentially relevant to the dopaminergic and neurodevelopmental hypothesis of schizophrenia." (PMID 31420036, 2019). "Glial cell line-derived neurotrophic factor (GDNF) and brain-derived neurotrophic factor (BDNF) are two widely studied families of neurotrophins in schizophrenia." (PMID 39886050, 2024). "The existing literature suggests that the disruption of glial cell line-derived neurotrophic factor (GDNF) and miRNA-29a is significant in schizophrenia." (PMID 38645418, 2024). "The structural plasticity induced by GDNF may contribute to learning and memory processes by altering the connectivity and activity of hippocampal circuits, which is interesting because there is evidence of a reduction in adult-born hippocampal granule cell neurons in schizophrenia." (PMID 38645418, 2024). "Plasma levels of glial cell line-derived neurotrophic factor (GDNF), a pivotal regulator of differentiation and survival of dopaminergic neurons, are reportedly decreased in schizophrenia." (PMID 38674063, 2024). "IL-1β, IL-2, IL-4, IL-6, BAFF, IFN-α, GM-CSF, NRG1-β1, and GDNF increased but TNF-α and NGF-β decreased in schizophrenia compared to healthy individuals." (PMID 37239308, 2023). "Thus, A2AR antagonism may alleviate schizophrenia symptoms by two complementary mechanisms: acutely via inhibition of enhanced GDNF-driven striatal dopamine release and chronically via downregulation of striatal GDNF expression." (PMID 35618883, 2022). "Lastly, we find that GDNF levels are increased in the cerebrospinal fluid (CSF) of first episode psychosis (FEP) patients and in post-mortem striata of schizophrenia patients." (PMID 35618883, 2022). "In this study, the relationship between cognitive functions and BDNF, GDNF, NGF and Klotho levels in 41 patients diagnosed with schizophrenia who had acute psychotic exacerbation and in 43 healthy controls was examined." (PMID 34763683, 2021). "BDNF, GDNF, NGF and Klotho levels were lower in schizophrenia patients than in healthy controls; and, in schizophrenia, on the 20th day of treatment, there was a statistically significant increase in BDNF compared to the 1st day." (PMID 34763683, 2021). "Brain-derived neurotrophic factor (BDNF), glial cell line-derived neurotrophic factor (GDNF) and neuronal growth factor (NGF) are among the most studied neurotrophic factors in schizophrenia." (PMID 34763683, 2021). "GFRA1 is a receptor of the neurotrophin GDNF which has been widely investigated in mood disorders (MDD and bipolar disorder), schizophrenia and treatment responses)." (PMID 21750702, 2011).